EZH2 (enhancer of zeste 2 polycomb repressive complex 2 subunit)
Diseases named in the same sentence as EZH2 in open-access papers (continued):
Sharing a sentence is not in itself a finding about the gene and the disease.
lymphoma (continued). "Overexpression of the human E(Z) homologue EZH2 has been observed in prostate cancer and lymphomas, and is linked to increased cell proliferation." (PMID 14970850, 2004). "PRC2-dependent repression of antigen processing pathways has previously been identified as a conserved mechanism for immune evasion by tumor cells that can potentially be counteracted by PRC2 inhibition, including in lymphoma cells carrying EZH2 gain-of-function mutations." (PMID 38658543, 2024). "We reason that expression of genes bound by high levels of MEN1/MLL1 is also hypersensitive to MEN1 inhibition, which could underline the preferential toxicity of MEN1 inhibitor to EZH2 mutant lymphoma cell lines." (PMID 37460547, 2023). "Mutations found more commonly in ABC or GCB subtypes respectively further add defining features and explanation to their course, such as N1 subtype appearing in ABC 95% of the time, or the observed co-occurrence of EZH2 mutations with BCL2 translocations in GCB type lymphomas." (PMID 36818048, 2023). "The biology of B cells that bear gain-of-function mutations in EZH2 make them predisposed to respond to EZH2 inhibitors; however, EZH2 wild-type (WT) lymphomas also arise from EZH2-dependent cells and the biological response to the EZH2 inhibitors is expected to occur in these WT tumors as well." (PMID 38096164, 2023). "Furthermore, both compounds not only target wild-type EZH2, but are also extremely sensitive to lymphoma cells harboring EZH2-activating mutations." (PMID 36076977, 2022). "The synthetic lethal relationship was first identified in SMARCB1 deficient rhabdoid tumors and lymphomas, in which tumor phenotypes could be rescued by inhibition of EZH2." (PMID 35326450, 2022). "In different human lymphoma cell lines, the mutation A677G in EZH2 showed analogous effects." (PMID 35326620, 2022). "All three inhibitors showed activity against lymphoma cells with EZH2 mutation." (PMID 34298959, 2021). "GSK126, a highly selective, S-adenosyl-methionine-competitive, small-molecule inhibitor of EZH2 methyltransferase activity, was also reported to show therapeutic effects in experimental and clinical settings including lymphoma with EZH2-activating mutations 17 and atrial fibrosis." (PMID 33391480, 2021). "EZH2 inhibitors can be used to treat EZH2 gain of function mutations in lymphomas." (PMID 33572577, 2021). "Individual examination of the EZH2, SUZ12, and EED genes showed that CRPC and prostate neuroendocrine carcinoma demonstrated an association with frequent alterations in each of the PRC2 encoding genes, while in GCB-DLBCL lymphoma a high correlation was found only with alterations in the EZH2 gene." (PMID 34202528, 2021). "EZH2 activating mutations in GCB lymphomas significantly alters the immune microenvironment." (PMID 35071240, 2021). "Furthermore, EZH2 GOF is closely associated with epigenetic silencing of CD58 expression on lymphoma cells, thus blocking the interaction with cytotoxic effector CD2+ T and NK cells and interrupting another avenue of immune control." (PMID 35071240, 2021). "The efficacy of tazemetostat for the treatment of malignant lymphoma has been validated in phase I and II studies, and a phase II study of tazemetostat showed high efficacy for follicular lymphoma with both wild-type and mutant EZH2 mutations." (PMID 33374737, 2020). "These GOF EZH2 mutations promote H3K27 hypertrimethylationand contribute to lymphoma pathogenesis." (PMID 32453339, 2020). "Clearly, most tumor types use EZH2 in support of tumor growth, yet EZH2 loss also occurs, particularly in some myelodysplastic syndromes, and mutations can drive neomorphic activity, particularly in lymphomas." (PMID 33003334, 2020).
lymphoma (continued). "In lymphoma and other malignancies, EZH2 gain-of-function mutations and overexpression are considered important drivers of oncogenesis because of their role in silencing tumor suppressor genes regulating apoptosis, cell cycle regulation, proliferation, migration and differentiation." (PMID 32408898, 2020). "Importantly, treatment with EZH2 inhibitors led to significant growth inhibition and cell killing, which was comparable to the activity of EZH2 inhibitors in lymphoma cells harboring gain-of-function mutations in EZH2." (PMID 32850364, 2020). "High expression levels of ezh2 are associated with tumor hallmarks so that the inhibition of EZH2 could be an attractive strategy for lymphoma treatments." (PMID 31921674, 2019). "Moreover, they show that SESTRIN1 is a direct target of the lymphoma-specific EZH2 gain-of-function mutation (EZH2Y641X)." (PMID 29057015, 2017). "In addition, EZH2 activating mutations are found to occur in some types of lymphoma, further rendering EZH2 as an appealing target in cancer therapy." (PMID 27882937, 2016). "Some examples of the SWI/SNF-PRC2/EZH2 oncogenesis hypothesis include malignant rhabdoid tumors (MRT) in which the SWI/SNF subunit INI1 (a.k.a. hSNF5, SMARCB1, BAF47) is inactivated, and in lymphomas with EZH2 activating mutations." (PMID 27125524, 2016). "Several inhibitors of the PRC2 activity have shown efficacy in EZH2-mutated lymphomas and are currently in clinical development, although the molecular basis of inhibitor recognition remains unknown." (PMID 27122193, 2016). "Finally, it has been reported that the combination of the EZH2 inhibitor E7438 with a corticosteroid has an anti-proliferative effect in GCB-like lymphoma cell lines and sensitizes EZH2 inhibitor-resistant cell lines, independently of EZH2 mutational status." (PMID 26497210, 2016). "EZH2 mutations can be detected in lymphomas and myeloid malignancies." (PMID 27023522, 2016). "Clinically, these EZH2 mutated lymphomas exhibit a particularly high levels of H3K27me3." (PMID 27316347, 2016). "Somatic mutations in EZH2 occur in ~3% of melanoma, which to date is the only other cancer type that contains the same activating Y646 mutation as lymphoma (equivalent tyrosine based on current NCBI protein reference sequence; NP_004447.2) that is the most frequent alteration." (PMID 26304929, 2015). "Recent sequencing studies have identified numerous mutations of EZH2 in a variety of leukemias and lymphomas, including follicular lymphoma (FL; 7%–22%), diffuse large B-cell lymphoma (DLBCL; 14%–21.7%), high grade B-cell lymphoma (18%), MDS/MPN (6%–13%), CMML (11.1%), T-ALL, and AML." (PMID 24622842, 2014). "In recent studies, missense mutations in EZH2 have been identified in a subset of lymphomas." (PMID 24367611, 2013). "Based on the encouraging activity of Tazemetostat against B‐cell lymphomas in phase I of NCT01897571, investigators aimed to investigate further whether specific lymphoma entities would exhibit enhanced efficacy and whether EZH2 mutational status would influence treatment sensitivity." (PMID 40181550, 2026). "Thus, lymphoma cells carrying Ezh2 mutations may reprogram the GC niche to allow for their own aberrant expansion in an FDC-dependent manner, and remodel the interaction between B cells, TFH and FDCs." (PMID 34456919, 2021). "Additionally, EZH2 has been reported to be subjected to gain of function mutations that increase global levels of H3K27me3 in lymphoma and rare cases of melanoma, and lastly EZH2 inhibitors are in active clinical trial for lymphoma." (PMID 30761216, 2018). "In the past years, several other highly specific EZH2 inhibitors have been characterized, three of which were shown to cause highly similar changes in the gene expression profile when used on a lymphoma cell line, indicating a common mechanism of action both on-target and off-target." (PMID 27634879, 2016).
lymphoma (continued). "In vivo studies using a humanized lymphoma mouse model demonstrated a synergistic anti-tumor effect of EZH2 degrader and anti-PD-1, which was attributed to apoptosis-related pathways." (PMID 40308579, 2025). "In this study, MS1943, a PROTAC-based EZH2 degrader, demonstrated notable efficacy in suppressing human lymphoma cell lines, especially Burkitt’s lymphoma, compared to the conventional EZH2 inhibitor, Tazemetostat." (PMID 40308579, 2025). "Preclinical studies showed that tazemetostat was effective in vitro and in vivo (including in xenograft models) against EZH2-mutant lymphoma." (PMID 40943058, 2025). "BCL6 has been reported to co-regulate GC formation and lymphoma cell survival with EZH2 and PRMT5, respectively." (PMID 39815148, 2025). "By establishing and analyzing isogenic lymphoma cells expressing WT or mutant-EZH2, we demonstrated the broad epigenetic phenotype mediated by this mutation, affecting a wide array of histone modifications other than lysine 27 methylations." (PMID 40504770, 2025). "Despite EZH2 being an established target in lymphoma therapy, further research remains needed to clarify the role of frequently observed EZH2 mutations in MDS and AML." (PMID 40562788, 2025). "The epistasis relationship uncovered here also raises questions regarding the advantage for lymphomas of simultaneous KMT2D and EZH2 mutations, which future investigations will help clarify." (PMID 40512686, 2025). "These phase II data provide level 2 evidence that EZH2-directed HMT inhibition can translate into durable clinical benefit in selected genetically defined lymphomas and sarcomas." (PMID 41335282, 2025). "Overexpression of EZH2 has also been confirmed in hematologic malignancies, such as lymphomas, with particularly high expression observed in Burkitt’s lymphoma." (PMID 40308579, 2025). "In this study, we present the application of CyTOF to reveal novel aspects of EZH2 gain-of-function and KMT2D loss-of-function mutations in lymphoma." (PMID 40504770, 2025). "This study compares the efficacy of a conventional EZH2 inhibitor with a PROTAC-based EZH2 degrader in human lymphoma cell lines." (PMID 40308579, 2025). "An example of this is TP53INP1, the expression of which has been shown to differentiate lymphomas with EZH2 mutations and BCL2 translocations from other lymphoma subtypes." (PMID 41497400, 2025). "In conclusion, our study provides a promising therapeutic strategy to improve lymphoma therapeutic efficacy by blocking immunological evasion that occurs by inhibition of EZH2." (PMID 40308579, 2025). "Recent research supports that EZH2 is one of key factors contributing to the pathogenesis of lymphoma." (PMID 40308579, 2025). "We evaluated the effects of an EZH2 degrader on seven lymphoma cell lines and observed significant reductions in cell viability compared to EZH2 inhibitor, particularly in Burkitt’s lymphoma cell lines." (PMID 40308579, 2025). "EZH2 GOF mutations were shown to promote lymphoid transformation and contribute to lymphoma cells’ proliferation and survival." (PMID 40504770, 2025). "The data reveal that impaired KMT2D and enhanced EZH2 activity have quite distinct effects on the lymphoma epigenome." (PMID 40512686, 2025). "To isolate the direct effects of EZH2 and KMT2D mutations, we utilized the patient-derived lymphoma cell line OCI-Ly7, which carry WT alleles of all the main epigenetic regulators that are known to be recurrently mutated in DLBCL." (PMID 40504770, 2025). "We show that mutant-EZH2 elicits extensive effects on the epigenome of lymphomas, beyond alterations to H3K27 methylations, and is epistatic over KMT2D mutations." (PMID 40504770, 2025).
lymphoma (continued). "Of note, due to the importance of its function, targeting EZH2 has been applied in EZH2 activation mutant lymphoma and diffuse intrinsic pontine glioma." (PMID 39072246, 2024). "The promising results with tazemetostat in EZH2 wild-type lymphoma support the exploration of EZH2 inhibition in other hematological malignancies." (PMID 38339323, 2024). "It is expected to be more efficient than EZH2-selective inhibitors in eliminating H3K27me3 and is highly effective against lymphomas." (PMID 38383791, 2024). "Although PRC2 inhibitors, such as tazemetostat, have demonstrated anti‐lymphoma activity in patients, the clinical efficacy is not limited to EZH2‐mutant lymphoma." (PMID 38229201, 2024). "We verified that our results in iMEFs were also representative of lymphoma by assessing the transcriptomic effects of PRC2 inhibition in EZH2-WT and EZH2Y646F-expressing OCI-Ly19 cells." (PMID 38658543, 2024). "EZH2 is the catalytic subunit of the histone methyltransferase Polycomb Repressive Complex 2 (PRC2), and its somatic activating mutations drive lymphoma, particularly the germinal center B‐cell type." (PMID 38229201, 2024). "As for NGS, it would be recommendable to study differential mutational patterns in TCF3 and ID3, which are recurrently mutated in BL, and EZH2, CREBBP, and KMT2D, which are mutated in other lymphomas." (PMID 37672206, 2024). "Actually, MYC can recruit EZH2 to miR-26a promoter and cooperatively repress miR-26a expression in lymphoma cells." (PMID 38561330, 2024). "Understanding the diverse mechanisms by which EZH2 contributes to lymphoma pathogenesis, including epigenetic regulation and interactions with the tumor microenvironment, provides valuable insights for targeting EZH2 in lymphoma treatment." (PMID 37752998, 2023). "In spite of the remarkable reduction of H3K27me3 in both EZH2 wild-type and mutant lymphoma cell lines, similar to other EZH2 inhibitors, EPZ005687 significantly inhibited the proliferation of mutant EZH2 cells only." (PMID 36900330, 2023). "We used MS1943, an EZH2 selective degrader, which successfully diminishes EZH2 levels in lymphoma cells." (PMID 37760442, 2023). "Clinical studies have demonstrated the potential of various EZH2 inhibitors, which target the methyltransferase activity of EZH2, for the treatment of lymphomas." (PMID 37752998, 2023). "EZH2 GOF mutations also induce CD58 epigenetic silencing in lymphoma cells, associated with a decreased NK cell activation, suggesting that lymphoma B cells harboring EZH2 mutations can escape both T cell and NK cell lysis." (PMID 38022603, 2023). "Next to genomic aberrations affecting epigenetic modifiers, such as EZH2, KMT2D, and CREBBP, transcription in is also rewired in GC-derived lymphomas via mutations in the gene encoding the transcription factor MEF2B." (PMID 38124747, 2023). "Overexpression of EZH2 has been observed in sarcomas, lymphomas, and cancers of the breast, colon, liver, lung, and prostate." (PMID 36622753, 2023). "Ezh2 GOF mutation cooperates with BCL2 deregulation (VavP-BCL2, Cγ1cre Ezh2Y641F/wt) to increase the frequency of lymphomas with features of GCB-DLBCL." (PMID 38022603, 2023). "Overexpression of EZH2 has been observed in lymphomas, sarcomas, and cancers of the breast, colon, liver, lung, and prostate." (PMID 36622753, 2023). "We continuously exposed the EZH2-mutant lymphoma cell line DB to increasing concentrations of EPZ-6438 for 6 weeks to develop an EPZ-6438-resistant line (DB-r)." (PMID 37460547, 2023). "Intriguingly, knock-down of IKZF1 sensitizes tumor cells in DLBCL to treatment with the EZH2 inhibitor tazemetostat, not only emphasizing its biological, but also a possible clinical impact in lymphoma." (PMID 37563306, 2023). "Coincidingly, Ezh2-mutant lymphomas were characterized by a drastically reduced T cell infiltration of the local lymphoma microenvironment." (PMID 38124747, 2023).
lymphoma (continued). "The results show that gastric mucous cells reached the highest EZH2 expression levels in normal human tissue cell lines, while lymphoid cancer cells (e.g., MOLT-4, HDLM-2) were highest in cancer cell lines." (PMID 36545914, 2023). "Recently, the application of EZH2 inhibitors in lymphoma and breast cancer has yielded promising results in treating cancer." (PMID 37268997, 2023). "This approach enabled the clustering of lymphomas with co-occurring MYD88- and CD79B mutations (MCD), BCL6 rearrangements and NOTCH2 mutations (BN2), EZH2 mutations and BCL2 rearrangements (EZB), as well as NOTCH1 mutations (N1)." (PMID 38124747, 2023). "Although EZH2 gene is often overexpressed in many solid tumors, as well as malignant lymphoma, a defective EZH2 function should be important in myeloid malignancies." (PMID 36835136, 2023). "EZH2 plays a significant role in lymphoma as the catalytic subunit of PRC2, regulating gene expression through histone methylation." (PMID 37752998, 2023). "Approximately one-third of these genes were also downregulated by MI-503 in another EZH2 mutant lymphoma cell line DB." (PMID 37460547, 2023). "The overall discrepancy in the efficacy of EZH2 inhibitors in lymphoma versus solid tumors, including TNBC in the context of primary tumor growth, is due to the lack of particular mutations (Y646, A682, and A692) in solid tumors that are present in lymphomas." (PMID 36446780, 2022). "Activating mutations in the SET domain of EZH2 (KMT6A) are seen in some lymphomas and levels of EZH2 are increased in many carcinomas, including breast and prostate, and in multiple myeloma, where high expression is associated with poor prognosis." (PMID 35406676, 2022). "For example, the combination of EZH2 inhibitor with HDAC inhibitor increased lymphoma cell line apoptosis." (PMID 36684449, 2022). "The studies have mostly addressed the EZH2-targeted treatments of lymphoma and melanoma or of tumor cell lines." (PMID 36077742, 2022). "It is likely that these EZH2-WT tumors harbor other genetic or epigenetic alterations that sensitize to EZH2 inhibition and/or that EZH2 dependency is “inherited” by lymphoma cells derived from the germinal center, as has been suggested." (PMID 35426374, 2022). "A new dual inhibitor against EZH1 and EZH2 (valemetostat) is effective against several malignant lymphomas, including ATL." (PMID 36239901, 2022). "EZH2, a central writer molecule involved in tumorigenesis and maintenance, was observed with genetic abnormalities and aberrant expression in several malignant lymphomas and solid tumors." (PMID 36239901, 2022). "EED226 was one of the first EED inhibitors reported and was found to specifically inhibit H3K27 methylation, either in lymphoma cells harboring WT-EZH2 or EZH2 mutants." (PMID 36076977, 2022). "A plethora of studies show the oncogenic functions of EZH2 in leukemias, lymphomas, and solid tumors (." (PMID 35395831, 2022). "Of VUS mutations, 3% led to an observable gain- or switch-of-function, including one with alterations in product specificity similar to those observed in a SET domain of EZH2, which is currently being targeted by therapeutics as a lymphoma treatment." (PMID 36323913, 2022). "EI1, an EZH2 inhibitor in lymphoma, is currently under development and it seems to inhibit cell growth and induce apoptosis and differentiation in lymphoma cells by reduction of H3K27me3 levels." (PMID 36338673, 2022). "The importance of the study of this gene is due to its role in the biogenesis of lymphomas and also because there are selective inhibitors targeting EZH2." (PMID 36230571, 2022). "EZH2 is a validated therapeutic target for some types of lymphoma, such as diffuse large B‐cell lymphoma, in which activating mutation of EZH2 is frequently detected." (PMID 35604910, 2022). "GSK126 and EPZ-6438, two EZH2 specific inhibitors, are under clinical investigation for treating lymphomas." (PMID 35137163, 2022).